RN7SKP226 (RN7SK pseudogene 226)
Gene: Miscellaneous RNA gene on chromosome 8 (128,220,504 to 128,220,803, forward strand). Ensembl gene ENSG00000201782.
Homologues: Orthologues: chimpanzee 7SK (96% identical), mouse Gm55975 (67% identical). Paralogues in human: 7SK (76% identical), RN7SKP217 (75% identical), RN7SKP255 (75% identical), RN7SKP71 (75% identical), RN7SKP9 (75% identical), RN7SKP203 (75% identical), RN7SKP22 (75% identical), RN7SKP95 (75% identical), RN7SKP90 (74% identical), RN7SKP180 (74% identical), RN7SKP269 (74% identical), RN7SKP275 (74% identical), and 284 more.
Diseases named in the same sentence as RN7SKP226 in open-access papers:
RN7SKP226 is named in the same sentence as 1 disease in open-access papers, as found by Europe PMC text mining. Sharing a sentence is not in itself a finding about the gene and the disease.
RN7SKP226 shares sentences with these, for which no sentence is quoted: cancer (1 paper).